CD4 (CD4 molecule)
Diseases named in the same sentence as CD4 in open-access papers (continued):
Sharing a sentence is not in itself a finding about the gene and the disease.
autoimmune disease (continued). "Similarly, several studies indicate that Th17 cells, a subset of CD4+ T-cells that produces IL-17, play a key role in the pathogenesis of various inflammatory and autoimmune diseases." (PMID 34602975, 2021). "Immunoglobulin G4-related disease (IgG4-RD) and systemic sclerosis (SSc) are rare autoimmune diseases characterized by the presence of CD4+ cytotoxic T cells in the blood as well as inflammation and fibrosis in various organs, but they have no established etiologies." (PMID 33648559, 2021). "HLA class II-associated autoimmune diseases are considered antigen driven (e.g., by wheat gliadin in celiac disease), although tissue pathology is not mediated by CD4+ T-cells only." (PMID 33863907, 2021). "Therefore, these can be used to treat autoimmune diseases through blockade of upregulated Kv1.3 channel in autoreactive human CD4+ TEM cells." (PMID 34658872, 2021). "However, a dysregulated response of CD4+ T cells can lead to the occurrence of various autoimmune diseases." (PMID 33777965, 2021). "Increasing our understanding of the effects of glycolysis and ROS synthesis in Th1 and Th17 CD4 T cell differentiation could give rise to novel targets for delaying T cell-mediated autoimmune diseases." (PMID 34276700, 2021). "This is supported by findings that CD4 CTL accumulate in autoimmune diseases." (PMID 34073458, 2021). "Therefore, it is conceivable that gut-derived iTreg cells can reach chronically inflamed tissues in a similar way that activated CD4+CD25+Foxp3+ nTregs are recruited during autoimmune disease development." (PMID 35919733, 2021). "Th1/Th2 were the first CD4+ T helper cell subsets determined to contribute to autoimmune diseases." (PMID 33717180, 2021). "T cell responses in autoimmune disorders are influenced by pregnancy, and hormonal changes during pregnancy could play a critical role in determining the effector CD4+ T cell cytokine profile at the fetomaternal interface." (PMID 34441010, 2021). "We found that the pathogenic activation of the previously ignorant GP-reactive CD4+ T cells in Alb-iGP_Smarta mice seemed to require several weeks of subclinical autoimmunity before the spontaneous clinical manifestation of self-sustained autoimmune disease." (PMID 33600378, 2021). "Opening a completely new avenue for investigation, we found that MC1-R is also present in CD4+ T cells, which are important for immune responses during host defense and play a central role also as drivers of autoimmune diseases and chronic inflammatory diseases such as atherosclerosis." (PMID 34868038, 2021). "A previous report showed that overnight or 24‐h fasting can blunt CD4+ Th cells activation and differentiation, which may be exploited as an intervention on auto‐immune diseases." (PMID 34705313, 2021). "However, many critical questions about the potential contribution of memory CD4+ T-cells to autoimmune diseases remain unanswered." (PMID 33936039, 2021). "Thus, the nature of the CD4 T cell epitopes driving T1D and other autoimmune diseases remained a puzzle, since these T cells appear to have escaped both control mechanisms." (PMID 33095259, 2021). "CD4+ T cells are key drivers of autoimmune diseases, including crescentic GN." (PMID 33598825, 2021). "The combination of vvDD-IL-23 and immune checkpoint blockade might induce autoimmune diseases since IL-23 promotes the development of an IL-17-producing CD4+ helper T cell subset." (PMID 34093846, 2021). "Research has found that leptin is Th17 necessary for lymphocyte differentiation; in addition, leptin and thymocytes from double-positive cells (CD4+ CD8+) to CD4+ differentiation of single positive cells-related Treg are needed to suppress the abnormal immune response in autoimmune diseases." (PMID 35027962, 2021).
autoimmune disease (continued). "To investigate whether expression of IRF4 by T cells contributes to mechanisms of T cell differentiation and immune regulation during an autoimmune disease, we generated mice with targeted deletion of irf4 in CD4+ T cells (CD4-IRF4KO)." (PMID 33803441, 2021). "The method we used to analyze CMV-reactivated CD4+ T cells may be extended to other conditions, such as autoimmune diseases and cancers." (PMID 34950144, 2021). "Thus, this CD47-SIRPα interaction between DCs and CD4+ T cells has the potential to be an important mechanism in the pathogenesis of autoimmune diseases." (PMID 34093583, 2021). "Therefore, it is not a surprise that the gene coding this protein was overexpressed in CD4+CD28null T lymphocytes which as was said above, is an expanded subset in autoimmune diseases, such as RA." (PMID 34202487, 2021). "Twenty-five years later, these cells were named regulatory T cells (Tregs) in a study that found athymic mice inoculated with purified CD4+CD25- T cells spontaneously developed autoimmune diseases whereas the transfer of CD4+CD25+ cells inhibited CD4-mediated autoimmunity in lymphopenic mice." (PMID 34177941, 2021). "Recent studies have shown that autoimmune diseases are closely related to CD4+ T helper cells (Th)." (PMID 33553436, 2021). "In addition, we have assessed the expression of candidate genes related to autoimmune diseases in thymic CD4+ and CD8+ T cells." (PMID 32393182, 2020). "Similarly to most common human MS manifestations (about 80%), RR–EAE in the SJL mouse is a CD4+ T-cell-mediated autoimmune disease directed against protein components of CNS myelin, resulting in a relapsing–remitting clinical course of paralysis." (PMID 32197530, 2020). "Likewise, in RASGRP1-deficient mice development of CD4 Treg cells in the thymus is severely impaired, and loss-of-function mutations of RASGRP1 was identified in autoimmune diseases." (PMID 31948396, 2020). "The increased proportion of CD5high cells among Egr2/3−/− MP CD4 T cells, and auto-reactive T cells and autoimmune disease in CD2-Egr2/3−/− mice suggests that these enriched clones may have high affinity for self-antigen." (PMID 32709717, 2020). "This hypothesis predicted that treatment of autoimmune disease-affected mice with pMHCII-NPs would elicit the formation and/or expansion of autoantigen-specific regulatory CD4+ T-cells." (PMID 33574822, 2020). "CD4+ T cells are the predominant cell population to orchestrate human innate and adaptive immune responses against infections, cancer formations, inflammations, and the developments of autoimmune diseases." (PMID 32878069, 2020). "Additionally, CD226 has also been demonstrated to be involved in the pathogenesis of autoimmune diseases by promoting self-reactive CD4+ T cell activation and triggering naïve CD4+ T cell differentiation and proliferation." (PMID 32983109, 2020). "In addition to affecting innate immune cells, testosterone is associated with shifts in the numbers, activities, and differentiation of CD4+ T cells in experimental models of allergy and autoimmune disease." (PMID 32645119, 2020). "Th17 is a group of IL-17-secreting CD4+ T-cells observed in inflammatory or autoimmune diseases." (PMID 32316255, 2020). "In fact, TGFβ is required to generate peripheral Treg cells by activating the canonical TGFβ/SMADs signaling; mice with Smad2 and Smad3 deletions on CD4+ T cells also developed severe autoimmune disease with reduced FOXP3 expression in the peripheral CD4+ T cells." (PMID 33419310, 2020). "Collectively, all the information suggests that the subpopulation of CD4+ CTLs may play an important role in inflammation of autoimmune disease." (PMID 33603736, 2020). "TRAPS-HP peripheral Tregs (CD4+Fox3+) were reduced in number and had a decreased suppressive capacity when compared with Tregs from healthy controls, features that are observed in many autoimmune disorders." (PMID 32380704, 2020).
autoimmune disease (continued). "Characterization of how sepsis also influences cells that function to suppress autoimmune disease, such as CD4 Tregs which are more resistant to sepsis-induced numerical loss than other CD4 T cell subsets, would also provide an interesting angle for interrogating the immunoparalysis state." (PMID 33191915, 2020). "Interestingly, Th17 cells have been considered as new CD4 helper T cell subsets that are essential in the pathogenesis of plenty of autoimmune diseases through animal models including RA, psoriasis, and multiple sclerosis." (PMID 33344450, 2020). "These ex vivo expanded, highly enriched Th-2+CD62L+CD4+iNKT cells may have a tremendous potential as novel cell therapeutics for several autoimmune diseases where quantitative and qualitative defects of iNKT cells are linked to the pathogenesis of the disease." (PMID 33329531, 2020). "In their study, the authors used tetramer staining to show that RA patients had significantly higher numbers of autoantigen-specific CD4+ T cells in peripheral blood than HCs30, again indicating a potential role for CD4+ T cells in autoimmune disease pathogenesis." (PMID 33277543, 2020). "Foxp3+CD4+ regulatory T cells (Treg) constitutes a key event in autoimmune diseases." (PMID 32646440, 2020). "Our results suggest the addition of IL-7 during antigenic stimulation with allogeneic dendritic cells can promote the expansion of CD62L+Th-2+CD4+ human iNKT cells that can be used as novel immunotherapeutic to control excessive inflammation to treat various autoimmune diseases." (PMID 33329531, 2020). "Th17 cells, another subset of CD4+ T-cells that reside at mucosal surfaces, play a significant role in immunity and the inflammatory response, including protecting against extracellular pathogens during autoimmune diseases." (PMID 32824563, 2020). "Interestingly, unlike pathogen-specific memory T cells, which are long-lived and highly proliferative, memory CD4+ T cells from autoimmune disease patients are more likely to undergo apoptosis and are less likely to proliferate, most notably for CD4+ TCM." (PMID 32106536, 2020). "CD4+IL-17+Th17 cells were once discovered to induce autoimmune disorders." (PMID 33015714, 2020). "An increased CD4/CD8 ratio is usually observed in the blood of patients with autoimmune diseases." (PMID 32392269, 2020). "Additionally, it will be essential to modulate CD4+ T cells for the treatment of other autoimmune disease such as multiple sclerosis (MS) and infection diseases, due to their dominant roles in orchestrate the innate and adaptive immune responses." (PMID 32878069, 2020). "An imbalance in the ratio of CD4+ T lymphocytes to CD8+ T lymphocytes may lead to the growth of autoimmune diseases." (PMID 32063984, 2020). "High expression of FR4 and CD73 are shared by anergic CD4+FoxP3- T cells and CD4+Foxp3+ Treg and both molecules are thought to be functionally involved in suppressing immune responses to self-antigens during pregnancy and in autoimmune disease models, in part by allowing the generation of Treg." (PMID 33329540, 2020). "In several other autoimmune diseases, such as lupus nephritis, idiopathic thrombocytopenic purpura, myasthenia gravis, and rheumatoid arthritis, treatment with rituximab significantly increased the growth of CD4+ CD25bright FoxP3+ Treg cells." (PMID 31428090, 2019). "CD39 expressing CD4+ T cells are important modulators of autoimmune diseases like MS." (PMID 31258540, 2019). "However, in addition to mediate adaptive immune responses against pathogens, CD4+ T cells also mediate autoimmune diseases." (PMID 31297117, 2019). "Furthermore, CXCL11 levels can predict CD4+ T-cell count, with increased levels detected in mixed cryoglobulinemia, Graves’ disease, and some autoimmune diseases." (PMID 31836011, 2019).
autoimmune disease (continued). "However, there are not studies addressing differences in the circulating numbers or function of all the main T CD4+ subsets in pAPS, such as Th1, Th2, Th17, and Tregs, which play important roles in autoimmune diseases." (PMID 30894863, 2019). "Enhanced CD4+ T cell effector function might be an important contributor to the development of autoimmune diseases in these mice." (PMID 32010133, 2019). "Immune dysregulation, polyendocrinopathy, enteropathy, X-linked (IPEX) syndrome is caused by mutations in FOXP3 (Forkhead-Box-Protein P3), a transcription factor that is expressed in a subset of thymic CD4+ T-lymphocytes which are required to maintain tolerance, and prevent autoimmune diseases." (PMID 31799221, 2019). "Lastly, infection and autoimmune diseases may influence both the count of Th17 cells and CD4+ Tregs as well as their IL-17A expression, we did, however, not factor those in as potential confounders." (PMID 31681282, 2019). "Double-negative T cells (CD4- CD8-) are proinflammatory cells in autoimmune diseases and are associated with the tolerance induction." (PMID 31019876, 2019). "Collectively, our findings reveal the innate-like pathogenic function of antigen non-related memory CD4+ T cells, which contributes to the development of autoimmune diseases." (PMID 30755603, 2019). "For example, in mainly CD4+ T cell-driven autoimmune diseases, a selective immunosuppression of these cells would leave anti-viral and anti-tumor reactive CD8+ T cells intact and therefore circumvent potential side effects of global T cell suppression as currently used." (PMID 31354474, 2019). "In this review, we discuss how CMV might potentiate and exacerbate autoimmune disease through the expansion of CD28null CD4 T cells." (PMID 30984377, 2019). "Suppression of miR-142 expression in CD4+ T cells from patients suffering from autoimmune diseases such as SLE predicts that PDE3B expression and activity may be enhanced in these cells and that this may underlie disease etiology." (PMID 30741720, 2019). "The Terg cells are implicated in a range of medical conditions like cancer and other autoimmune diseases, but are also known to be the immunosuppressive subset of CD4+ T cells that maintain the immune homeostasis by regulating the numerous facets of immune response." (PMID 31875150, 2019). "This may be a result of potentially more aberrant methylation of B cells than CD4 T cells, as demonstrated in another autoimmune disease, Sjogren’s syndrome." (PMID 31443559, 2019). "Interestingly, activated CD4+ T cells have been shown to increase levels of soluble IL-6R via IL-6R shedding; this mechanism is thought to have a role in the development of autoimmune diseases, which are often mediated by autoreactive T cells." (PMID 31276585, 2019). "However, the input of other IL-31-producing cells, especially CD4+ T cells, in these autoimmune diseases still needs to be elucidated in terms of IL-31-mediated immunomodulatory roles." (PMID 31281316, 2019). "Gene modification of CD4+ T cells could be used to induce Treg subsets for therapeutic intervention in autoimmune diseases." (PMID 29535721, 2018). "Treatment of naive CD4+ T cells with 1,25(OH)2D potently induces the development of Treg, and this may exert beneficial effects in autoimmune disease and host-graft rejection." (PMID 29853961, 2018). "In contrast to CD8 T cells, for which it is considered prototypic, cytotoxicity has much more recently been recognized as a relevant function of CD4 T cells with far reaching implications, not only for infectious disease, but also autoimmune disease and cancer." (PMID 30044874, 2018). "Thus, NAD is one of the major metabolic signals which serve as checkpoint for CD4+ T cell differentiation with anti-tumor properties and can be used to treat autoimmune diseases such as MS, IBD and chronic and inflammatory diseases." (PMID 30692989, 2018).
autoimmune disease (continued). "Furthermore, HSD has been shown to drive autoimmune disease and to exacerbate experimental autoimmune disease by inducing the activation of IL-17-producing CD4+ helper T cells (Th17)." (PMID 29614818, 2018). "Naïve CD4+ T cell differentiate into effector and regulatory subsets of helper T (Th) cells in various pathophysiological conditions and modulate tissue inflammation in autoimmune diseases." (PMID 30692989, 2018). "In addition, alterations in the number and function of CD4+Foxp3+ Treg cells have been reported in most autoimmune diseases as well as in other immune-mediated conditions." (PMID 30116758, 2018). "However, mogamulizumab also reduced the number of CCR4+ regulatory CD4 T cells, which was occasionally observed as a severe autoimmune disease." (PMID 29212930, 2018). "Recently, it has been addressed that CXCR5+CD4+ T cells are detected in organs that are affected by autoimmune disorders, such as systemic lupus erythematosus and Sjogren’s syndrome, suggesting that aberrant Tfh cells may induce autoimmunity." (PMID 29709026, 2018). "Meanwhile, it is known that a fine balance between effector CD4+ T cells and immunosuppressive regulatory CD4+ T cells (Tregs) affects the immune homeostasis considerably, whereby the levels and functions of these cells were shown to be disturbed in autoimmune diseases." (PMID 30563559, 2018). "Interestingly, transfected CD4+ T lymphocytes are used as the preferred vector in experimental gene therapy to treat autoimmune diseases in animals." (PMID 29568705, 2018). "Our findings indicate that Klf1 and Egr2 are modulators of PD-L1-mediated immune suppression in CD4+ T cells and might provide new insights into therapeutic targets for autoimmune diseases and malignancies." (PMID 29728568, 2018). "Breakdown of CD4+ T-cell tolerance is crucial in the development of autoimmune diseases." (PMID 30622543, 2018). "Since CD4+ T cell homeostasis is disturbed in autoimmune diseases and IgD is a critical mediator of homeostasis, we hypothesized that CP-25 could rebalance this CD4+ T cell homeostasis." (PMID 29410624, 2018). "On contrary, regulatory subsets of CD4+ T cells, which include Foxp3+ regulatory T cells (Tregs) and type 1 regulatory T (Tr1) cells, suppress effector T cell functions and contribute to resolution of tissue inflammation in autoimmune diseases." (PMID 30692989, 2018). "CD4+NKG2D+ T cells are associated with tumour, infection and autoimmune diseases." (PMID 28224733, 2017). "Here we found that TGFβ expression was also up-regulated in the RA samples, suggesting that TGFβ also could induce FGF2 expression in infiltrated CD4+ T cells in the autoimmune disease." (PMID 28765647, 2017). "CD4+ T cells are critical for host defense, but in addition to their key role as helper cells within the immune system, these cells can also be troublesome in that they can drive autoimmune diseases, e.g., IBD, MS and allergies." (PMID 29285231, 2017). "Interleukin (IL)-22+CD4+T (Th22) cells play crucial roles in the pathogenesis of autoimmune diseases and infectious diseases, although the role of Th22 cells remains largely unclear in children with hand, foot, and mouth disease (HFMD) caused by enterovirus 71 (EV71)." (PMID 28030850, 2017). "Multiple sclerosis (MS) is an autoimmune disease characterized by inflammation of the central nervous system, destruction of the myelin sheath around the axon of neurons and finally paralysis mediated by myelin specific CD4+ T cells." (PMID 28095433, 2017). "CD4 CTLs also have the potential to exacerbate autoimmune diseases." (PMID 28280496, 2017). "For example, ex vivo expanded polyclonal CD4+CD25+FoxP3+ Tregs are successfully used in hematopoietic stem cell transplants to prevent graft vs host disease are also evaluated in the treatment of autoimmune disease." (PMID 29225598, 2017). "CD4+ T cells are essential in inflammation and autoimmune diseases." (PMID 28095433, 2017).